HMGB1 (high mobility group box 1)
Diseases named in the same sentence as HMGB1 in open-access papers (continued):
Sharing a sentence is not in itself a finding about the gene and the disease.
depression (continued). "Furthermore, ds-HMGB1 has been shown to induce depression in a kynurenine-pathway-related manner and, moreover, the oxidation of fr-HMGB1 induces the activation of the kynurenine pathway, resulting in depressive behaviour." (PMID 37298365, 2023). "Thus, interesting associations about HMGB1 and RAGE have been observed mainly in animal models of depression, but few such studies have been performed using blood samples from human patients with depression." (PMID 37337402, 2023). "Thus, HMGB1 is involved in depression induced by inflammatory diseases, and it is possible that changes in peripheral blood HMGB1 can be detected in depressive patients with those diseases." (PMID 37337402, 2023). "However, since our findings also suggest multiple, potentially counteracting, roles of HMGB1 in this behavioral change, a further understanding of HMGB1 regulations and actions is warranted to exploit these findings for drug development for depression." (PMID 37443823, 2023). "As gasdermin D is reportedly crucial for chronic mild stress-induced depression-like behavior, it could mediate extracellular HMGB1 release from mPFC neurons upon repeated social defeat stress." (PMID 37443823, 2023). "Findings from the animal experiment have indicated that activation of HMGB1 could promote depressive-like behaviors in stress models of depression." (PMID 35733802, 2022). "The HMGB1 inhibitors GL and EP can improve depression-like behaviors." (PMID 36388178, 2022). "Another possible mechanism of HMGB1-mediated depression involves damage to dopaminergic neurons." (PMID 36388178, 2022). "The results have shown that CRS procedures obviously induced depression-like behaviors, which might be triggered by the neuroinflammation through the stress-induced up-regulation of the expression of HMGB1 and IBA-1 in the hippocampus." (PMID 35733802, 2022). "In our study, an interesting finding drew our attention that HMGB1 and Cx36 might interact with each other mutually in the development of depressive disorder." (PMID 35089644, 2022). "GZA binds directly to HMGB1, inhibits the extracellular cytokine activity of HMGB1, and alleviates the inflammatory response; thus, it may have potential in ameliorating depression." (PMID 35496318, 2022). "Cx36 and HMGB1 might mutually promote each other in the development of depressive‐like behaviors so that inhibition of them might be of benefit to depressive disorder." (PMID 35089644, 2022). "As such, damaged neurons or psychological stressors release danger associated molecular patterns (DAMPs) including high mobility group box 1 (HMGB1), mtDNA, ATP and the S100 proteins which trigger TLR-associated pathways and present a maj or risk factor for depression." (PMID 31749681, 2019). "In addition, low dose administration of lipopolysaccharide (LPS) to mice, as a model of depression, led to HMGB1 translocation from the nucleus to the cytoplasm, while blockage of HMGB1 abrogated the depressive-like behavior induced by LPS." (PMID 26733805, 2015). "HMGB1 may influence depression through pathways other than those mediated by childhood trauma." (PMID 40557138, 2025). "Therefore, inhibiting the activation of microglial HMGB1, which in turn alleviates the inflammatory response and neuronal damage, may represent a feasible strategy for the treatment of depression." (PMID 40406924, 2025). "These research findings present new perspectives and approaches to treating adolescent depression, indicating that by regulating the expression level of HMGB1, it may be possible to significantly improve depressive symptoms in patients, bringing new breakthroughs to clinical treatment of depression." (PMID 40557138, 2025). "Additionally, previous research has suggested that biomarkers like S100β, HMGB1, and NSE may not only reflect the progression of depression but also indicate an increased risk of neurodegenerative diseases associated with chronic depression." (PMID 39513898, 2024).
depression (continued). "Furthermore, icariin alleviates neuroinflammation in the hippocampus of mice with depression by inhibiting the high mobility group box-1 (HMGB1)/receptor for advanced glycation end-products (RAGE) signaling pathway and activating the X-box binding protein 1 spliced (XBP1s)/NF-κB signaling pathway." (PMID 38915473, 2024). "In addition, it is now known that depression in the offspring of toxoplasmosis-infected mouse mothers can be alleviated with ginsenoside Rh2, which reduces depression by inhibiting microglia activation through an HMGB1-related signalling pathway." (PMID 37298365, 2023). "Thus, the roles of endogenous HMGB1 in chronic stress-induced depression-related behaviors remain unknown." (PMID 37443823, 2023). "Thus, contrary to previous reports suggesting its pro-depressive role, our experiments suggested that endogenous extracellular HMGB1 in the brain could suppress chronic stress-induced depression-like behaviors." (PMID 37443823, 2023). "Although this study focused on HMGB1 and sRAGE, a comprehensive analysis of changes in DAMPs and PRRs, including investigation of the ratio of DAMPs to PRRs, may help elucidate the relationship between depression and inflammation in the future." (PMID 37337402, 2023). "Indeed, HMGB1 release from neurons has been shown in psychologically stressed rodents, and a sterile, acellular inflammatory reaction is well characterized in animal models of depression." (PMID 38082296, 2023). "However, as TLR2/4-mediated microglial activation in the mPFC is crucial for social avoidance induced by repeated social defeat stress, extracellular HMGB1 in selective brain regions, such as the mPFC, could promote depression-like behaviors." (PMID 37443823, 2023). "The activation of HMGB1 could promote depressive-like behaviors in stress models of depression." (PMID 35733802, 2022). "Moreover, previous studies have suggested that hesperidin and glycyrrhizic acid could amend chronic stress-induced depression-like behavior in mice by suppressing the activity of high-mobility group box 1 (HMGB1), a common biomarker for neuroinflammation." (PMID 36159556, 2022). "Since neuronal injury, glutamate excitotoxicity, and enhanced HCs activity were closely related to the development of depressive disorder, we further speculated that Cx36 might be the mediator in the process of HMGB1 mediated depressive‐like behaviors based on our previous work." (PMID 35089644, 2022). "Therefore, the present investigation was to estimate whether BA treatment possessed the antidepressant-like effects on CUMS induced depression by inhibiting inflammation through down-regulation of HMGB1/TLR4/NF-κB signaling pathway." (PMID 30658416, 2019). "By amplifying inflammation, the HMGB1/NLRP3 axis contributes to both the onset and persistence of depression, positioning it as a potential therapeutic target for inflammation-related depression subtypes." (PMID 40688353, 2025). "Inflammatory pathways, including the HMGB1/NLRP3 axis, contribute to the pathophysiology of depression." (PMID 40688353, 2025). "HMGB1 activates the microglial Notch1/Hes-1 pathway in CRS mice, promoting neuroinflammation and anxiety and depression-like behaviors." (PMID 39789446, 2025). "Previous experiments have shown that DACA has effects similar to those of HMGB1 inhibitors in suppressing the HMGB1/NF‐κB/NLRP3 pathway, thereby alleviating depression." (PMID 40406924, 2025). "In addition, one study on multimodal psychotherapeutic in-patient therapy for depression found it to be effective in patients with high cytokine production of IFNγ and IL-10, among others, while no significant changes were observed in the levels of other cytokines (including HMGB1)." (PMID 37298365, 2023). "HMGB1, a putative ligand for TLR2/4, has been suggested to promote depression-related behaviors under acute stress." (PMID 37443823, 2023).
depression (continued). "Animal models have shown upregulation of HMGB1 and RAGE in the brain or blood, suggesting the involvement of these proteins in depression pathophysiology." (PMID 37337402, 2023). "It has also been identified the significantly upregulated expression of HMGB1 in the serum and cerebral cortex of chronic unpredictable mild stress (CUMS)-induced depression model." (PMID 35733802, 2022). "It has also been identified the significantly upregulated expression of HMGB1 in the serum and cerebral cortex of chronic unpredictable mild stress (CUMS)-induced depression mouse model." (PMID 35733802, 2022). "Depression is a common comorbidity of NP; anti-HMBG1 mAb and glycyrrhizin (a HMGB1 inhibitor) can ameliorate depression." (PMID 31819042, 2019). "In this study, we evaluated the effects of DACA on depression‐like behavior in CUMS‐induced mice and explored whether its action is mediated by the inhibition of HMGB1/NF‐κB/NLRP3 signaling pathways, which are involved in neuroinflammation." (PMID 40406924, 2025). "Given prior evidence linking elevated HMGB1 to depression and stress-related neuroimmune dysregulation, it was hypothesized that ECT might exert therapeutic effects by downregulating HMGB1-mediated inflammatory pathways or modulating sRAGE expression." (PMID 40969698, 2025). "This research aims to elucidate the underlying molecular mechanisms and signaling pathways, establishing a theoretical foundation for considering HMGB1 as a novel therapeutic target for CRS-related anxiety and depression and providing clear guidance for future clinical applications." (PMID 39789446, 2025). "However, there is no specific study focused on assessing the effect of ω-3 PUFAs on S100β, HMGB1, and NSE in depression." (PMID 39513898, 2024). "There have not been studies specifically dedicated to investigating the protective effects of ω-3 PUFAs on specific biomarkers such as S100β, HMGB1, and NSE in depression across animal models as well as pre-clinical and clinical research specifically related to depression." (PMID 39513898, 2024). "HMGB1 binds to TLR4, leading to the recruitment and promotion of NF-κB, thereby activating the transcription of inflammatory cytokines, chemokines, and adhesion molecules, and promoting the development of depression." (PMID 39114351, 2024). "It has been reported that HMGB1 and RAGE are upregulated in animal models of depression." (PMID 37337402, 2023). "Repeated social defeat stress induced depression-related behavior in the control littermates, but this behavior was not significantly induced in forebrain neuron-specific HMGB1 knockout mice." (PMID 37443823, 2023). "On the other hand, activation of corticosteroid receptors of astrocytes leads to the release of neuroinflammatory mediators such as high-mobility group box-1 (HMGB1), of importance because neuroinflammation is considered a mechanism contributing to depression-like behaviors." (PMID 35652516, 2023). "Overactivation of inflammatory responses and increased levels of inflammatory mediators like interleukin (IL)−1β, IL‐6, tumor necrosis factor alpha (TNF‐α), the acute phase reactant (CRP), and high mobility group box 1 (HMGB1) were seen in both patients and rodents with depressive disorder." (PMID 35089644, 2022). "In addition, both the Hamilton Depression Rating Scale (HDRS) and the Hamilton Anxiety Rating Scale (HAM-A) scores were strongly positively correlated with HMGB1 serum levels." (PMID 35743957, 2022). "Therefore, our present study established the depression rat model of CRS and aimed to investigate the antidepressant mechanism of acupuncture of modulating the neuroinflammation induced by HMGB1." (PMID 35733802, 2022). "Given the complex nature of depression and the multifactorial aspects of both ω-3 PUFAs and the biomarkers in question, more targeted studies are necessary to explore how ω-3 PUFA supplementation might affect HMGB1, S100β, and NSE levels in individuals with depression." (PMID 39513898, 2024).
depression (continued). "Notably, acupuncture significantly alleviated the depression-like behaviors and reversed the high expression of HMGB1, Iba-1, and TNF-α in CRS rats, which indicates the antidepressant effect of acupuncture and provides new experimental evidence for new therapies in the treatment of depression." (PMID 35733802, 2022).
pulmonary fibrosis (52 papers, 2011 to 2026). Chronic progressive interstitial lung disorder characterized by the replacement of the lung tissue by connective tissue, leading to progressive dyspnea, respiratory failure, or right heart failure. "Previous studies have suggested that HMGB-1 is significantly associated with idiopathic pulmonary fibrosis (IPF)." (PMID 30558126, 2018). "Likewise, we demonstrated in the rat model of pulmonary fibrosis, the increased expression of HMGB1 was closely associated with the generation of extracellular matrix components, accompanied by increased expression of TGF-β." (PMID 36699071, 2022). "Second, we found that gefitinib was effective in reducing pulmonary fibrosis in mice, which might be associated with the HMGB1/NOXs-ROS/EGFR-MAPKs-AP-1/NF-κB signal." (PMID 29849916, 2018). "Considering a recent report that the loss of RAGE contributes to pulmonary fibrosis, the increase of HMGB1 in alveolar fluids itself may induce fibrogenesis through other HMGB1 receptors, such as the Toll-like family of receptors (TLRs), TLR4, TLR2, or TLR9." (PMID 21637372, 2011). "Moreover, they found that HMGB1 induced lung fibroblast proliferation, which may be the underlying mechanism of pulmonary fibrosis." (PMID 23617783, 2013). "Taken together, these findings support a model in which PS-NPs induced ferroptosis in alveolar epithelial cells drives fibroblast activation and pulmonary fibrosis through paracrine signals, including HMGB1, oxidized lipids and profibrotic cytokines." (PMID 41560817, 2026). "The NLRP3 inflammasome has also been shown to regulate epithelial-mesenchymal transition in the development of pulmonary fibrosis, while HMGB1 promotes fibroblast proliferation and collagen accumulation." (PMID 40688353, 2025). "Animal studies confirm that blockade of RAGE or HMGB1 signaling significantly reduces collagen deposition and inflammation in lung tissue, highlighting this pathway as a potential therapeutic target for pulmonary fibrosis." (PMID 40988754, 2025). "The receptor for advanced glycation end-products (RAGE) is a multi-ligand receptor predominantly expressed on type-II alveolar epithelial (AT2) cells, and its ligand HMGB-1 is highly up-regulated during pulmonary fibrosis." (PMID 40988754, 2025). "Studies have demonstrated that TGF-β1/Smad2/3 axis is involved in EMT triggered by HMGB1 in BLM-induced pulmonary fibrosis." (PMID 39008169, 2024). "Gefitinib has the potential to alleviate lung fibrosis induced by BLM via the HMGB1/NOXs-ROS/EGFR-MAPKs-AP-1/NF-κB pathway." (PMID 39008169, 2024). "Recent research has identified the signaling molecule HMGB1 as a critical factor in the fibrotic changes observed in systemic sclerosis, as well as liver, kidney, and lung fibrosis." (PMID 39331598, 2024). "Recent studies also found exogenous HMGB1 participated in the epithelial-mesenchymal transition via the PI3K/Akt/mTOR pathway in pulmonary fibrosis." (PMID 38469295, 2024). "Polyclonal anti-HMGB1 antibodies have also been reported to decrease lung inflammation and fibrosis in bleomycin-induced pulmonary fibrosis study models." (PMID 39682695, 2024). "Atazanavir sulfate reverses cell proliferation induced by EMT and prevents pulmonary fibrosis by inhibiting HMGB1/TLR signaling." (PMID 39008169, 2024). "In the radiation-induced pulmonary fibrosis, pneumonocytes release high mobility group box 1 protein (HMGB1) after lung injury." (PMID 35111363, 2022). "The expression of HMGB1 is up-regulated in pulmonary fibrosis and participates in the occurrence and development of pulmonary fibrosis." (PMID 36699071, 2022). "MiR-627 attenuates TGFβ1-induced proliferation of normal human primary lung fibroblasts by downregulating HMGB1 and inhibiting the NF-κB pathway, thereby alleviating the development of pulmonary fibrosis." (PMID 36163195, 2022). "HMGB1-targeting compounds have been used in pulmonary fibrosis models, but the clinical efficacy of these compounds remains to be determined." (PMID 35886594, 2022).